TGFB1 (transforming growth factor beta 1)
Diseases named in the same sentence as TGFB1 in open-access papers (continued):
Sharing a sentence is not in itself a finding about the gene and the disease.
tumor (continued). "Collectively, these findings indicate a potential utility of plasma Tgfβ1 levels as a predictor for MO-/PMN-MDSC ratio across tumor patients." (PMID 41360769, 2025). "In summary, TBX3high tumor cells promoted the infiltration of CAFs to form an immunosuppressive microenvironment through increased TGFβ1 secretion." (PMID 39897553, 2025). "For example, in prostate cancer, both tumor- and stromal-cell-induced TGFβ1 act as activators in the transformation of MSCs into CAFs." (PMID 40805183, 2025). "Conventionally, M2-polarized TAMs facilitate tumor immune evasion through IL-10/TGFB1 secretion or ARG1 overexpression." (PMID 40959090, 2025). "TGFβ1 represents a critical therapeutic target as a key cytokine involved in immune suppression and tumor progression." (PMID 40641297, 2025). "Under acidic tumor microenvironment conditions, a marked increase in TGFβ2 compared to TGFβ1 was observed." (PMID 39992949, 2025). "Conditional knockout Tgfβ1 in B cells reduced tumor growth and correlated with reduced regulatory T cells." (PMID 40356924, 2025). "Of note, TGFβ1 suppresses epithelial growth in normal tissues while promoting tumor progression in advanced cancers." (PMID 40291908, 2025). "TGFB1's dual role—initially suppressing tumour development but later promoting invasion through immunosuppression and epithelial‐mesenchymal transition—illustrates the context‐dependent nature of inflammatory mediators in cancer progression." (PMID 40682474, 2025). "The assessment of markers associated with immune-suppressive activities in splenic granulocytes (CD11b+Ly6G+) showed elevated mRNA levels of Il10, Vegfa, Tgfb1, and Arg1 in the tumor-bearing vehicle-control group compared to naïve mice." (PMID 41282257, 2025). "Although our data reveal the role of TGFβ1+ Treg cells in tumor progression, we also recognize that the complexity of tumor progression can be better understood by comparing the characteristics of superficial tumors, the invasion front, and metastatic sites." (PMID 40891683, 2025). "Similar to the previous findings, TPP1 positive macrophages secrete TNF and TGFB1 acting on tumor cells, thereby enhancing the proliferation of tumor cells." (PMID 40620715, 2025). "Cancer-associated fibroblasts and macrophages within the tumor stroma release several growth factors that induce the EMT, such as TGFβ1, PDGF, EGF, and HGF." (PMID 39941895, 2025). "CSR‐related genes (COL1A1, LOXL2, LUM, FN1, and TGFB1) reflect extracellular matrix deposition and stromal activation, hallmarks of invasive tumor behavior." (PMID 41407509, 2025). "SBF2-AS1 enhances tumor progression by sponging miR-361-5p, leading to derepression of TGFβ1 and promoting cancer cell proliferation and migration." (PMID 41437175, 2025). "In our experiments, only for MDA-MB-231, which mimics triple-negative BC, we found that the addition of TGFβ1 to the heterotypic cellular tumor model suppressed PB-NK cell activity and increased tumor cell proliferation." (PMID 40710292, 2025). "TGFβ1 is tumor-suppressive in early cancer development, but, in established tumors, it allows for tumor survival by creating immunosuppressive microenvironments, by increasing angiogenesis, and by regulating epithelial-to-mesenchymal transition." (PMID 40141091, 2025). "Research conducted on TC has demonstrated that transforming growth factor beta 1 (TGFβ1), a multifaceted cytokine secreted by tumour cells, directly contributes to the influx of TAMs." (PMID 41301715, 2025). "TGFβ1 siRNA LNPs modified with CE1.5, CE2.5, and TPGS2.5 can efficiently inhibit TGFβ1 mRNA and protein expression in A549/T cells in vitro, and they can accumulate and play a role in the tumor tissue of nude mice." (PMID 38258086, 2024).
tumor (continued). "On the other hand, immunohistochemistry assessment of human BC tissues showed significant increase in TGF-β1 expression, and it was mainly localized at the tumor edges and lymph node, indicating TGFβ1 role in promoting invasion and metastasis." (PMID 39351229, 2024). "Several analyses have shown that TGFB1 has a dual effect on carcinogenesis, acting as a tumor suppressor in the early stages and a tumor promoter and metastasis propagator in the later stages of BC." (PMID 39390525, 2024). "Collectively, these findings demonstrate that TGFB1-dependent LRRC15-positive CAFs dictate the tumor-fibroblast setpoint to promote tumor growth." (PMID 38892190, 2024). "FGF7 showed positive correlations with markers like ENDRB and TGFB1, suggesting its influence on immune cell infiltration and activity in the tumour milieu." (PMID 39063239, 2024). "We evaluated expression of progesterone receptor (PR), progesterone receptor membrane component 1 (PGRMC1), relaxin-2, and transforming growth factor beta 1 (TGFβ1) in tumor tissue from 92 women with HGSC parous (n = 73) and nulliparous (n = 19)." (PMID 38578428, 2024). "Vascular endothelial growth factor (VEGF) and transforming growth factor beta 1 (TGFβ1) secreted by tumor cells induce the endothelial cell junction opening of the endothelial cell junctions interfering with the VE-cadherin and β catenin." (PMID 39035739, 2024). "Tumour cells are capable of escaping the immune system reaction with the help of tumour-infiltrating regulatory T-cells (Tregs) by releasing immunosuppressive cytokines, namely IL-10 and TGFβ1." (PMID 38200509, 2024). "Secretion of TGFβ1 from tumor cells contributes to an immune suppressive TME by recruiting MDSCs and inhibiting cytotoxic T cells." (PMID 39518137, 2024). "Selective inhibition of TGFβ1 activation overcomes primary resistance to ICB therapy by altering tumor immune landscape." (PMID 38085441, 2024). "In tumour microenvironments, cancer cells increase B7-H4 expression in response to hypoxia and transforming growth factor β1 (TGFβ1); IL-6 and IL-10 can also stimulate B7-H4 mRNA expression in macrophages." (PMID 39571901, 2024). "Tumor tissues from VD3-deficient patients exhibited lower levels of β-catenin and TGFβ1, along with higher levels of CYP24A1 compared to VD3-normal patients." (PMID 38360633, 2024). "TGFβ1 is a multifunctional cytokine that plays a pivotal role in hematopoiesis, tumor development, and immune regulation." (PMID 38919521, 2024). "The expressions of vimentin, α-SMA, and TGFβ1 have been reported as prognostic markers or therapeutic targets for different tumor types." (PMID 38791274, 2024). "Transforming growth factor-beta 1 (TGF-β1) is one of the key cytokines involved in promoting tumour growth, angiogenesis, and immunosuppression." (PMID 38903497, 2024). "Transforming growth factor β1 (TGFB1) is mainly expressed in human tissues and can be synthesized and secreted by almost all cells, often upregulated in tumor cells." (PMID 38441550, 2024). "Tumour cell-derived soluble factors, such as TGFβ1 inhibit adipogenesis of adipose-derived mesenchymal stem cells (AD-MSCs) while increasing the fibroblastic differentiation followed by ECM deposition." (PMID 38783165, 2024). "Pericytes sGC inactivation resulted in a significant reduction of TGFβ1 expression in both ECs and pericytes, consequently driving the marked expansion of tumor-suppressive CD105neg CAFs." (PMID 38528180, 2024). "We also tested serum GM-CSF and TGFβ-1 levels on day 14 to examine changes in these immunosurveillance molecules where different expression levels can either promote anti-tumor immune responses (GM-CSF) or lead to immunosuppression (TGFβ-1)." (PMID 38267626, 2024). "SMAD4, a primary tumor suppressor gene, is a pivotal component of the transforming growth factor beta 1 (TGFB1) pathway." (PMID 39113194, 2024).
tumor (continued). "Amongst the differentially expressed EMT genes from that study, we find overlap with PTPRK-regulated genes including TGFB1, COL6A1, GPX3 and KLK10, as well as genes encoding LSR and PKP2, both of which are hyperphosphorylated in PTPRK KO tumours." (PMID 38904097, 2024). "In contrast, patients with metastatic lesions showed significantly higher levels of TGFB1 expression compared to primary tumours (p < 0.00001)." (PMID 38855324, 2024). "CCL5 and TGFB1 CSF concentration was moderately to strongly negatively correlated with tumor volume, as well as with Koos grade." (PMID 39272860, 2024). "In early stages of tumor development, tumor cells respond to the antimitotic and pro-apoptotic effects of TGFβ1." (PMID 38085441, 2024). "Our findings, in conjunction with previous studies, show that the signaling pathway involving IL22 and TGFB1 helps establish a microenvironment that promotes epithelial-mesenchymal transitions, malignancy progression, and tumor formation." (PMID 38456503, 2024). "Tumor-derived fibroblasts had a greater amount of endogenous TGFβ1 mRNA and collagen I mRNA and protein, compared with distal from patient RDEB119." (PMID 38462666, 2024). "Here, the authors show that tumor extracellular vesicles mediate mitochondrial DNA transfer to CECs, initiating mitochondrial activation and RelA-induced TGFβ1 expression, leading to tumor progression." (PMID 38688896, 2024). "We also analyzed the expression of other Th2 cytokines besides TGFβ-1 (IL-4 and IL-6) in spleen and tumor samples, but treatment with mHAdLyp.sT didn’t lead to any significant changes when compared to the buffer group (data not shown)." (PMID 38267626, 2024). "Subsequently, the increase in reactive oxygen species (ROS) generated by OXPHOS activates the NF-κB signaling pathway, which drives TGFβ1 transcription and protein secretion in normal CECs and turn promotes tumor progression." (PMID 38688896, 2024). "Dual inhibition of TGFβ1 and PD-L1 combined with radiotherapy remodeled the tumor microenvironment via increasing tumor-infiltrating leukocytes." (PMID 38324026, 2024). "In later stages TGFβ1 acts as a tumor promoter by modulating genomic instability, angiogenesis, lymphangiogenesis, immune suppression, immune evasion, epithelial-mesenchymal transition, endothelial-mesenchymal transition, and cell motility." (PMID 38085441, 2024). "As compared with the control groups, we observed an increase in the lifespan of animals and a decrease in the tumor size, as well as a decrease in the level of TGFB1 IL-10 factors in the blood plasma." (PMID 39767665, 2024). "Collectively, these results strongly suggest that tumor cells increase FAM3C levels through TGFβ1-Smad2/3 pathway in neutrophils during their interaction, and FAM3C-mediated tumor cell EMT is through JNK-ZEB1/Snail signaling activation." (PMID 37056931, 2023). "Molecular analysis showed that ROBO1 knockout or SLIT2 overexpression suppresses the transforming growth factor beta 1 (TGF‐β1)/β‐catenin signaling pathway in both tumor cells and macrophages." (PMID 35838343, 2023). "Additional factors that are expressed in BC tissues in a fashion that positively correlates with both the intensity of angiogenesis and tumor aggressiveness include TGFβ-1, pleiotrophin, placental growth factor, and PDGF." (PMID 36834641, 2023). "Mechanistically, TFAP2A directly binds to the CD133 promoter to ignite tumor stem-like properties in HCC cells and synergizes with periostin/TGFβ1 positive feedback loop to further boost tumor stemness." (PMID 37291585, 2023). "The expression of CLDN5 was strongly linked with that of immune checkpoint genes, such as TGFβ1, C10orf54, and ADORA2A in most tumor types, including STAD, COAD, and ESCA." (PMID 37286335, 2023).
tumor (continued). "Osteoclasts’ activation induces bone resorption, resulting in the release of TGFβ1 deposited in the bone extracellular matrix, which in turn promotes the proliferation of tumor cells and thus feeds forward the cycle of tumor growth and bone remodeling." (PMID 36835198, 2023). "Eosinophils synthesize and release epidermal growth factor and TGFβ1 to induce tumor growth and EMT." (PMID 37833255, 2023). "We observed that TGFB1 was co-expressed with proteins involved in angiogenesis and tumor immune escape in ccRCC, indicating that the alternative angiogenesis driven by TGFB1 resulted in Sunitinib resistance." (PMID 37460463, 2023). "The probability of interaction between tumor cells and fibroblast receptor-ligand pairs was higher than that of thyroid cells, especially in TGFB1/ACVR1/TGFBR1, FGF18/FGFR1, BTC/EGFR, BMP8A/BMPR1A/BMPR2, and BMP8A/BMPR1A/BMPR2." (PMID 37733241, 2023). "Among various constitutively- and BCR/CD40-mediated factors secreted, tumour subsets co-express two important immunoregulatory cytokines, IL10 and TGFβ1, both associated with a memory B cell phenotype." (PMID 36973425, 2023). "The VV-treated TGFβ1 overexpressing tumors had a significantly reduced survival as well as an increased tumor growth compared with VV-treated EV tumors." (PMID 37552475, 2023). "Our analysis also identified a subset of tumor-infiltrating pDCs in most of the MF samples that expressed TGFB1, ICOSLG, and LILRA4." (PMID 37669110, 2023). "Myeloid derived suppressor cells (MDSCs) and immunosuppressive regulatory T cells (Tregs) are recruited to the tumor region by TGF-β1 (transforming growth factor beta-1) and granulocyte–macrophage colony-stimulating factor (CSF) secreted by tumor cells." (PMID 37568713, 2023). "Tgfb1 was upregulated by several cell types within the TME in early tumor stages, and TAMs were major producers of Tgfb1 in advanced tumors." (PMID 37798557, 2023). "As previously reported, MSCs, when mixed with tumor cells in a tumor-related microenvironment, differentiate into cancer-associated fibroblasts (CAFs) that produce VEGF, IL-6, TGFβ1, etc., resulting in pro-tumor activity." (PMID 37681882, 2023). "Molecular analysis showed that SLIT2 overexpression or ROBO1 deletion suppresses the transforming growth factor‐beta 1 (TGF‐β1)/β‐catenin signaling pathway in both tumor cells and macrophages." (PMID 35838343, 2023). "The MSCs increased in vivo tumor growth and also increased intra-tumoral expression of bFGF, TGFβ1, hepatocyte growth factor (HGF), MMP2, and MMP9." (PMID 37569686, 2023). "Due to their target genes were mainly focused on EMT, miR-200 family are associated with tumor metastasis, for instance, zinc-finger E-box-binding homeobox 1 (ZEB1) and transforming growth factor β1 (TGFβ1)." (PMID 37333450, 2023). "Transforming growth factor beta-1 (TGFβ-1) is a cytokine that exerts pleiotropic effects on tumor progression, angiogenesis, and other biological processes." (PMID 37190188, 2023). "This adds to the previously established pleiotropic role of TGFβ1 as a cytokine, which orchestrates cellular crosstalk and plasticity in the tumor microenvironment." (PMID 38055067, 2023). "Afterwards, the immunofluorescence staining was further utilized to evaluate the in vivo TGFβ1 level of PANC02 tumor section from the mice treated with IS-Micelles at 24 h post-irradiation." (PMID 37120615, 2023). "As expected, HMOX1 and TGFB1 were upregulated in tumor and the related ROC curves showed the great performance of prediction." (PMID 37653101, 2023). "For example, human Wharton’s jelly MSC-Exos (hWJ-MSC-Exos) limited liver failure (LF) and protected hepatocytes by inhibiting epithelial-tumor mesenchymal transition and inactivating the TGFβ1/SMAD2 pathway." (PMID 36768406, 2023). "Mechanistically, co-culture with tumor cells increases FAM3C levels in neutrophils regulated by TGFβ1-Smad2/3 signaling activation, and FAM3C promotes tumor cell EMT through JNK-ZEB1/Snail pathway." (PMID 37056931, 2023).
tumor (continued). "High expression of TGFβ1 in tumor frequently correlates with inferior survival, even when cytotoxic T lymphocyte infiltration is rich." (PMID 36674809, 2023). "On the other hand, we found that anti-PD-L1 antibody treatment reduces TGFβ1 expression in tumor cells with PD-L1 low expression." (PMID 38152616, 2023). "Previous studies have shown that bFGF contributes to increased invasiveness of tumor cells by enhancing the ability of fibroblasts to produce various growth factors such as TGFβ1 and matrix metalloproteinase (MMP-9)." (PMID 38152616, 2023). "Among them, the CSF1-CSFR1 axis was present with significant effects on macrophage activation and polarization, whereas TGFB1-EGFR axis was reported to mediate tumor migration and invasion." (PMID 36864399, 2023). "To further investigate TGFB1 expression across a broad subtypes of blood cancers, we retrieved 40 datasets with matched tumor and normal samples encompassing 22 blood cancer types (n = 9101, Pan-Hem-Diff cohort)." (PMID 37925591, 2023). "PEG10 (paternally expressed gene 10) promotes tumor invasion and metastasis, and is a major regulator in TGFB1-induced EMT." (PMID 36980828, 2023). "Consistently, the results of clonogenic assays revealed that HMOX1 or TGFB1 knockdown reduced the potential for colony formation by tumor cells." (PMID 37653101, 2023). "Tumor cells secrete a cytokine mixture containing TGFβ1, which acts as a strong immunosuppressant by blocking the maturation of monocytes through its CSF-1 (colony-stimulating factor 1) content." (PMID 37108109, 2023). "The analysis of two independent cohorts of CLL B cells and PBMCs from a total of 97 patients demonstrated that CD5+CD19+CD27+ memory CLL B cells produce and secrete IL10 and TGFβ1, as part of the tumour cell secretome." (PMID 36973425, 2023). "As a result, we observed a significant enrichment of TGFB1 in both the immune response group and the neoplasms group within the FBmiR miRNA list." (PMID 37761827, 2023). "To test the effects of TGFβ directly on responsiveness to VV treatment, we overexpressed TGFβ1 into the MEERvvS tumor line to generate MEERvvS-TGFβ OE and an EV control (MEERvvS-EV)." (PMID 37552475, 2023). "It should be noted that the prognostic impact of TGFB1 expression was evaluated using bulk expression profile data, which averages the diverse cells within each tumor, making the percentage of tumor cells hard to determine and masking the influences of TME." (PMID 37925591, 2023). "In brief, our results illustrate that coculturing tumor cells with platelets increases the level of TGFβ1 (secreted by both platelets and tumor cells) in the culture medium." (PMID 37705745, 2023). "As a pleiotropic cytokine, TGFβ1 is intricately involved in tumor initiation, progression, and metastasis." (PMID 38201290, 2023). "Inside the tumor tissue, the three established isoforms of TGFβ, namely, TGFβ1, TGFβ2, and TGFβ3, are released by cancer cells or CAFs." (PMID 38111465, 2023). "IFN-Y induces polarization of TAMs, TNF-α, and lipopolysaccharide (LPS) into the M1 (classically activated/anti-tumor) macrophage phenotype and IL-4, IL-190, TGFβ1, and PGE2, into the M2 (alternatively activated/pro-tumor) macrophage phenotype." (PMID 37637998, 2023). "Our findings from two different cell lines suggest that anti-PD-L1 antibody treatment increases TGFβ1 expression in tumor cells with PD-L1 expression by more than 50%." (PMID 38152616, 2023). "Tumoral cells can indeed promote an elevated production of immunosuppressor cytokines (such as IL-10 and TGFβ1) that downregulate the anti-tumor response at different levels." (PMID 37239941, 2023). "Combining GTEx dataset with TCGA and TARGET pan-cancer datasets, we then systematically compared TGFB1 expression between tumor and adjacent normal tissue across 34 cancer types." (PMID 37925591, 2023). "Similar results were observed for the levels of serum TGFβ-1, which is involved in fibrosis and tumor progression." (PMID 38012636, 2023).